SOX17 (SRY-box transcription factor 17)
Diseases named in the same sentence as SOX17 in open-access papers (continued):
Sharing a sentence is not in itself a finding about the gene and the disease.
tumor (continued). "Kaplan–Meier survival curves indicated that the overall and disease‐free survival rates of patients with tumor endothelial SOX17 immunoreactivity were more favorable than those of SOX17‐negative groups but without statistically significant differences." (PMID 39385307, 2024). "SOX17 has also been shown to upregulate tumor angiogenesis via increased VEGFR2 expression and inhibition of Sox17 leads to marked decreases in tumor progression, angiogenesis, and vascular density in multiple tumor models." (PMID 38028440, 2023). "The gene expression analysis of the full set of 11,003 samples from 33 TCGA tumor types identified three genes (MUC16, PAX8 and SOX17) that showed gene expression ranges of OSCA samples that did not overlap with the gene expression ranges of samples deriving from most of the other tumor types." (PMID 35954427, 2022). "Together, these in vitro and in vivo results showed that SOX17 is an upstream transcriptional suppressor of NRF2, and increased NRF2 protein expression could promote aggressive cell behaviors and accelerate tumor growth." (PMID 36310172, 2022). "For the other three genes (MUC16, PAX8 and SOX17) in combination, their RNA quantity may distinguish OSCA from other 29 tumor types." (PMID 35954427, 2022). "Therefore, we further examined SOX17 and NRF2 protein expression in the tumor tissues derived from endoscopic biopsy samples of good or poor CCRT responders." (PMID 36310172, 2022). "Moreover, SOX17 reduced the irradiation tolerance of ESCC cells by reducing HIF1α expression via the MALAT1-miR-199a axis, and attenuated tumor formation in nude mice." (PMID 35614065, 2022). "Overall, our findings reveal the previously uncharacterized anti-tumor effect of ASMTL-AS1 in TNBC, in which ASMTL-AS1 acts as a ceRNA sponging miR-1228-3p and elevating SOX17, resulting in the inactivation of Wnt/β-catenin signaling, thereby inhibiting TNBC tumorigenesis and progression." (PMID 34006305, 2021). "In the regulatory network, several hub genes with maximum intramodular connectivity were identified (i.e., GATA6, SOX17, MEF2C, and SRF), which might propose novel insights for tumor angiogenesis." (PMID 34869004, 2021). "SOX17 was expressed in the tumor thrombus of CRPC; thus, it was hypothesized that decreasing SOX17 expression inhibits metastasis." (PMID 33791203, 2021). "Furthermore, three-gene combinations detected even the smallest lung nodules, with the combination of CDO1, SOX17, and HOXA7 having the overall best performance, while the combination of CDO1, TAC1, and SOX17 was best in tumor sizes less than 1.0 cm." (PMID 32138766, 2020). "Tumor markers IRF4, SOX17, and MEF2C are all involved in the development of various tumors." (PMID 32420368, 2020). "However, the tumor derived-organoids were positive for glandular markers MUC1 and SOX17, which confirmed their glandular origin." (PMID 32552764, 2020). "Four genes (TFPI2, SOX17, GATA4, and FBN2) satisfied the criteria of “cancer-specific methylation” with high-frequency methylation in cell lines, no/undetectable methylation in normal oral mucosa, and frequent methylation in primary OSCC tumor samples." (PMID 31405379, 2019). "We provide evidence that SOX17 downregulates MAML3 and Wnt signaling, which may reduce tumor cell proliferation and improve patient outcome." (PMID 27738313, 2016). "Immunohistochemical (IHC) analyses of human normal endometrium (n=30), atypical hyperplasia (n=30) and EC tumor specimens (n=60) showed that SOX17 expression was very low or absent in late EC stages, with high expression of Wnt pathway proteins." (PMID 27738313, 2016). "Thus, we screened for changes in SOX17 and SOX2 expression as an indicator of a successful transition of TCam-2 cells to an EC-like tumor." (PMID 24386123, 2013).
tumor (continued). "For example, in cells and animal models, SOX17 poorly expresses in ESCC cells and tumor tissues; at the same time, overexpression of SOX17 could sensitize ESCC irradiation-resistant cells to irradiation, cisplatin and concurrent chemoradiation therapy treatment." (PMID 35614065, 2022). "In addition, ZVI@CMC could serve as a DNMT inhibitor to restore SOX17/NRF2 axis, and the combination of ZVI@CMC with radiation treatment significantly augmented anticancer efficacy to inhibit the tumor growth of CCRT resistant cancer." (PMID 36310172, 2022). "Among these genes, TFPI2, SOX17, and GATA4 were frequently hypermethylated in both OSCC and oral cancer patient samples in a cancer-specific manner, suggesting that these genes may play a role as tumor suppressors in OSCC." (PMID 31405379, 2019). "In contrast, Sox17 was completely absent from normal intestinal crypts and could not be detected in P-Rspo3 tumours, accurately reflecting the gene expression observed in organoids." (PMID 28695896, 2017). "Notably, in CCA tumor tissues, the promoter of SOX17—a negative regulator of the WNT–β-catenin pathway—was found to be hypermethylated when compared with adjacent healthy tissue, and this methylation status correlated with a poorer prognosis following tumor resection." (PMID 40980689, 2025). "Based on our previous observation that SOX17 overexpression could sensitize ESCC cells to radiation treatment, we further investigated whether ZVI@CMC combined with radiation treatment could augment anti-tumor efficacy and overcome resistance in NRF2high ESCC cells." (PMID 36310172, 2022). "The comparable SOX17 expression patterns in reserve cells and in the remnants of IMM support the general opinion that reserve cells are the progenitors for IMM and may therefore provide additional evidence for the reserve cell as the progenitor of cervical (pre)neoplasia." (PMID 32644288, 2020). "However, the absence of any cases displaying loss of heterozygosity or multiple SOX17 mutations (i.e. no second hit mutations), and the functional differences between the missense and frameshift mutations indicate that the role of SOX17 mutations in EEC is unlike classical tumor suppressor genes." (PMID 28978154, 2017).
cancer (90 papers, 2009 to 2026). A tumor composed of atypical neoplastic, often pleomorphic cells that invade other tissues. "A low expression of SOX17 in certain cancer types has been linked to a bad prognosis for the patient." (PMID 38136277, 2023). "The hypermethylation of the SOX17 promoter is associated with abnormal activation of the Wnt signaling pathway, which is known to contribute to tumorigenesis in multiple cancer types." (PMID 38067304, 2023). "Recent work has suggested several cancer variants associated with gain-of-function variants in SOX17 based on the screening of cancer genomic databases, furthering the reach of SOX variants into somatic variant risks." (PMID 36672963, 2023). "Further, more than 80% of cancer patients have methylation of SOX17 promoter, which is negatively associated with the accumulation of nuclear CTNNB1." (PMID 36457029, 2022). "SOX17, initially identified as a transcription factor associated with endoderm and fetal foregut development, has recently emerged as a significant player in cancer progression by orchestrating cellular reprogramming across various cancer types." (PMID 39279027, 2024). "Interestingly, accumulating evidence shows that SOX17, expressed at low levels in many different types of cancers, is associated with the radiotherapeutic sensitivity of ESCC." (PMID 35614065, 2022). "While it is reportedly mutated in 8% of ECs, the role of SOX17 in this cancer is still unclear." (PMID 27738313, 2016). "The findings revealed that SOX17 upregulated Klotho gene expression in this cancer by binding to the Klotho gene promoter." (PMID 40004457, 2025). "SOX17 immunoreactivity was minimal in all cancer cells, except for five non‐mucinous adenocarcinomas in situ with morphological features of type II alveolar epithelial cells." (PMID 39385307, 2024). "While cervical adenocarcinoma displays low SOX17 expression, suggesting its potential role as a tumor suppressor, the intricate relationship between genes, proteins, and cancer development is far from fully understood." (PMID 39767561, 2024). "In the present study, we aimed to unveil the expression of SOX17 in the cancer cells and TME of human LUAD." (PMID 39385307, 2024). "Dysregulation of SOX17 is a major component in the development and progression of numerous types of cancer, including endometrial, esophageal, and breast." (PMID 38136277, 2023). "The promoter region of SOX17 is often found to be hypermethylated in several types of cancers such as cholangiocarcinoma, lung cancer, gastric cancer, liver cancer, and breast cancer." (PMID 38067304, 2023). "We reported recurrent methylation changes in the promoters of several genes, many previously implicated in cancer, including FAM83A and SEPT9 (hypomethylation), as well as PCDH7, NKX2-1, and SOX17 (hypermethylation)." (PMID 37742993, 2023). "Among these genes, SRY (sex determining region Y)-box 17 (SOX17) is a transcription factor important for esophagus tissue development and is hypermethylated in human cancers." (PMID 36497337, 2022). "SOX17 is a transcription factor that enhances differentiation in the endoderm, and its expression is reportedly reduced in cancer stem cells." (PMID 35047127, 2022). "The single genes CD59, RAP80 and SOX17 have been reported to serve as DNA-repair-related biomarkers to predict patients’ prognosis in ESCA or subtypes of this cancer." (PMID 34257547, 2021). "It has been shown that Oct4, SOX2 and SOX17 mutants are able to dimerize, forming heterodimers that contribute to tumorigenesis across different cancers." (PMID 33152990, 2020). "The promoter hypermethylation of CDO1, TAC1, HOXA7, and SOX17 were detected more frequently in the plasma of cancer patients compared with controls." (PMID 32138766, 2020). "Up until now, it has been demonstrated that SOX17 shows almost undetectable expression levels in a variety of cancers cell lines and primary tumors." (PMID 33152990, 2020).
cancer (continued). "Similar to other types of cancers, it has also been proved that the SOX17 protein is involved in the Wnt-signaling pathway in NSCLC." (PMID 33152990, 2020). "Together these mRNA and protein results indicated that SOX17 overexpression sensitized ESCC resistant cells to anti-cancer treatment via down-regulation of DNA repair or damage-responsive genes." (PMID 30777052, 2019). "The SRY-box containing gene 17 (SOX17) is considered as a regulator in stemness maintenance and a suppressor in some malignant tumors." (PMID 29970906, 2018). "As for CRC, the significantly higher APC, FOXA1, RARβ2, RASSF1A, SCGB3A1, SEPT9 and SOX17 methylation levels in cancer patients are in line with previous publications, although divergent results have been reported for MGMT." (PMID 30261643, 2018). "A systematic down-expression of SOX17 in multiple cancer types was observed in across the ten datasets interrogated (p = 0.002)." (PMID 29970906, 2018). "Three DEG were also statistically significant after FDR correction: Npc1 in cellular processes and Ifitm10 and Sox17 in genes involved in cancer." (PMID 29950665, 2018). "As a canonical Wnt antagonist, SOX17 is epigenetically inactivated by promoter methylation in many cancers, regulating proliferation, the cell cycle and angiogenesis during cancer progression." (PMID 27738313, 2016). "MiR-371-5p was necessary for SOX17 mediated cancer-related traits and SOX2 was a functional target of miR-371-5p." (PMID 25868860, 2015). "Interestingly, a recent study reported that MCAM was transcriptionally activated by SOX18, a subset of SOX17 interactome, which was indispensable in cancer metastasis." (PMID 40778650, 2025). "In these SOX17‐positive cases, cancer cells ubiquitously exhibited strong SOX17 immunoreactivity." (PMID 39385307, 2024). "In five of the 83 LUAD tissue specimens, cancer cells exhibited SOX17 immunoreactivity." (PMID 39385307, 2024). "Indeed, SOX17 has previously been recognized as a negative regulator of the canonical Wnt signaling pathway and has demonstrated antitumor properties in certain cancer contexts." (PMID 39279027, 2024). "Furthermore, SOX7 and SOX17 have been demonstrated to possess antiproliferative functions in cancer cells." (PMID 37511076, 2023). "This abnormal methylation of SOX17 is particularly prevalent in non-small-cell lung cancers (50% of cases) and esophageal squamous cancers (nearly 90% of cases), further supporting its involvement in cancer development." (PMID 38067304, 2023). "SOX17 promoter methylation has been suggested to offer crucial information for cancer prognosis." (PMID 33833773, 2021). "In these types of cancer, a low SOX17 expression has been correlated with a poor patient prognosis." (PMID 33152990, 2020). "Since low expression of SOX17 occurred in ESCC radio-resistant cells, we next examined whether re-expression of SOX17 could sensitize their responses to anti-cancer treatments." (PMID 30777052, 2019). "Since low expression of SOX17 occurred in CCRT non-responder ESCC patients, we next examined whether expression of SOX17 could increase sensitivity of ESCC cells to anti-cancer therapies." (PMID 30777052, 2019). "Together, these results suggested that SOX17 may sensitize cells to anti-cancer treatments through in vivo binding to the promoter and thus transcriptional down-regulation of DNA repair genes and damage responsive genes." (PMID 30777052, 2019). "It has been reported that forced expression of SOX17 reduces proliferation of cancer cell lines." (PMID 28978154, 2017). "Based on these data, we hypothesize that SOX17 may be involved in the mechanism of cancer resistance to cisplatin chemotherapy." (PMID 27065754, 2016). "SOX17 expression is reduced in some cancer cells and was correlated with poor prognoses." (PMID 27738313, 2016). "However, the molecular mechanism of SOX17 in regulating apoptosis of cancer cells after CDDP treatment is not fully understood." (PMID 27065754, 2016).
cancer (continued). "The methylation status of LINE1 and SOX17 DNA in gastric juice-derived exosomes was found to accurately reflect the methylation status of nuclear DNA in the corresponding tumors, indicating a role in the noninvasive diagnosis of cancer." (PMID 26582468, 2015). "SOX17 regulates proliferation, cell cycle and angiogenesis during cancer progression." (PMID 25868860, 2015). "MiR-371-5p was necessary for SOX17 mediated cancer-related traits in CRC cells." (PMID 25868860, 2015). "Additionally, epigenetically regulated SOX17 may contribute to the abnormal activation of the Wnt signaling pathway in human cancer." (PMID 31405379, 2019). "Among them, SOX17, forkhead, and homeobox genes might be crucial and may contribute to the different behaviour of small putative cancer stem cells from borderline ovarian cancer despite their comparable size and morphology to small stem cells from “healthy” ovaries." (PMID 27703207, 2016). "Thus, a deeper understanding of the regulation of Sox17 gene expression might provide a basis for the development of novel anti-angiogenic cancer therapies." (PMID 26630461, 2015). "SOX17 immunoreactivity was significant in LUAD, harboring a CD8+ T‐cell‐rich cancer stroma compared with cases of CD8+ T‐cell poor stroma (p < 0.01)." (PMID 39385307, 2024). "In summary, both studies highlight the crucial role of SOX17 in the early development of CRC, particularly in the formation of precancerous lesions and the evasion of immune surveillance by cancer cells." (PMID 39279027, 2024). "In estrogen receptor-positive cancer with mass lesion type, CCL3L1 (21-fold), SNHG12 (11-fold), and MIR206 (sevenfold) were upregulated, and MIR597 (265-fold), MIR126 (12-fold), and SOX17 (fivefold) were downregulated." (PMID 37391754, 2023). "As expected, significantly more methylated epialleles of SOX17, CDO1, TAC1, and HOXA7 were detected in cancer patients compared to the benign group." (PMID 37039321, 2023). "SOX factors such as SOX17 and SOX9 seem also play supporting roles in initiating human cancers by providing primitive stem-cell-like states." (PMID 34768751, 2021). "Consistent with DNA methylation profiles in plasma, methylation of CDO1, TAC1, SOX17, and HOXA7 were detected more frequently in patients with cancer compared with controls." (PMID 32138766, 2020). "In particular, we selected target genes known to be critical in cancer development, namely TCF7, DKK1, WISP1, MYCC, and SOX17." (PMID 32283844, 2020). "The methylation detection rate of CDO1, TAC1, SOX17, and HOXA7 were significantly higher in cancer group than in the benign group (p < 0.001)." (PMID 32138766, 2020). "We identified that TFPI2, SOX17, and GATA4 are frequently hypermethylated in human OSCC cells in a cancer-specific manner and that the transcriptional expression of these genes is regulated by promoter hypermethylation in OSCC." (PMID 31405379, 2019). "Bisulfite sequencing analysis confirmed the cancer-specific methylation of the TFPI2, SOX17, and GATA4 promoters in the OSCC cell lines and tumors but not in the normal oral mucosa samples." (PMID 31405379, 2019). "We identified the transcriptional expression of 9 genes regulated by promoter hypermethylation in OSCC and finally provided 3 genes (TFPI2, SOX17, and GATA4) that were frequently hypermethylated in primary OSCC tumors in a cancer-specific manner." (PMID 31405379, 2019). "We observed interesting relationships among the most methylated genes (TFPI2, SOX17, and GATA4) in OSCC cell lines and primary tumors in a cancer-specific manner." (PMID 31405379, 2019). "However, the role of SOX17 in anti-cancer therapy response remains unclear." (PMID 30777052, 2019).